AR (androgen receptor)
Diseases named in the same sentence as AR in open-access papers (continued):
Sharing a sentence is not in itself a finding about the gene and the disease.
hyperandrogenism (continued). "Hyperandrogenism, in combination with up-regulation of AR expression, also leads to antiproliferative effects in glandular epithelium by suppressing oestrogen-dependent glandular mitosis despite the presence of oestrogen." (PMID 37569402, 2023). "It is possible for the C11-oxy C21 steroids to contribute to active C11-oxy C19 steroids, leading to the activation of the AR, specifically in pathophysiologies characterized by hyperandrogenism." (PMID 38203272, 2023). "Despite androgen excess, PCOS in humans is associated with reduced ovarian AR expression, indicative of alternative signalling through ERs, either directly or via aromatization." (PMID 37171897, 2023). "They proposed that short-term stimulation of androgen will increase AR expression in vitro or in vivo, followed by inhibition of AR expression due to the increased AR-mediated reaction in the chronic hyperandrogenism of PCOS." (PMID 36499085, 2022). "Hyperandrogenism was controlled by androgen receptor inhibitors; the GnRH analog was used to inhibit the development of central precocious puberty." (PMID 36431124, 2022). "For instance, another in vivo study reported that AR is highly expressed in PCOS animal models due to induction by androgen, suggesting an association between PCOS and hyperandrogenism." (PMID 35885010, 2022). "Male patients or female patients with androgen excess are more likely to activate AR signaling pathway." (PMID 35069767, 2022). "prenatally androgenized (PNA) models or testosterone-treated models were used as PCOS-like models for hyperandrogenism basis, which would highly increase the expression of AR." (PMID 34248847, 2021). "Aldosterone antagonists, androgen receptor antagonists, 5α-reductase inhibitors, and synthetic progestogens are used to reduce hyperandrogenism." (PMID 33334002, 2020). "We discuss the most prominent clinical features of androgen excess and correlate them with studies on androgen receptor (AR) alterations." (PMID 28551687, 2017). "In previous studies, we found prenatal T treatment from days 30-90 of gestation increases granulosa cell androgen receptor expression in antral follicles and is supportive of functional ovarian hyperandrogenism." (PMID 27357284, 2016). "Longer polyglutamine chains have been shown to hinder the transactivation activity of AR in vitro, while short polyglutamine chains lead to enhanced AR activation resulting in hyperandrogenism." (PMID 23227263, 2012). "Furthermore, AR knockout (ARKO) mouse models exhibiting complete or partial androgen receptor insufficiency confer protection against hyperandrogenism-induced phenotypic manifestations of PCOS in female mice." (PMID 40385288, 2025). "Taking into account that CYP19A1 mRNA increased under hyperandrogenism treatment, we hypothesized that AR may bind to the promoter of CYP19A1 gene to regulate aromatase expression." (PMID 40898340, 2025). "Overall, our study sheds light on the intricate interplay between androgens and sex steroid hormones in the regulation of endometrial receptivity development and emphasises the detrimental effects of hyperandrogenism on fertility through its influence on AR, ERα and PR expression patterns." (PMID 39337689, 2024). "Controlling hyperandrogenism may require the use of androgen receptor antagonists or oral contraceptives containing drospirenone, which effectively reduce the synthesis of adrenal and ovarian androgens." (PMID 39081437, 2024). "Moreover, hyperandrogenism stimulates the transcription of AR in mononuclear cells to release more inflammatory factors." (PMID 38152131, 2023). "Particularly in PCOS patients, hyperandrogenism also increases the expression of the androgen receptor (AR) and the AR co-regulatory protein MAGEA11 in endometrial tissue, leading to a delay in endometrial decidualisation due to impaired differentiation of endometrial stromal cells." (PMID 37569402, 2023).
hyperandrogenism (continued). "Additionally, at the highest doses representing female (5 nM) and male (100 nM) hyperandrogenism, differences in AR mRNA between 46XX and 46XY decreased, possibly due to receptor desensitization, resembling effects seen during clinical hyperandrogenism." (PMID 38139211, 2023). "Overall, our finding demonstrates the significant influence of circadian rhythms on PCOS occurrence, suggests that MTNR1A and AR play vital roles in pathological progression of hyperandrogenism, and broadens current treatment strategies for PCOS in clinical practice." (PMID 36353509, 2022). "Afterwards, the expression of AR might be inhibited due to the increased activity of AR in a chronic hyperandrogenism environment of PCOS." (PMID 35885010, 2022). "There results suggest that impaired ovarian function might lead to uterine AR-mediated abnormal implantation in pregnant rats with hyperandrogenism." (PMID 34180022, 2021). "As circulating testosterone levels are elevated in PNA-treated mice, and AR expression in the brain appears to be positively autoregulated by androgens, it is possible that hyperandrogenism in the PNA mouse is the driver of increased AR expression in NPYARN neurons." (PMID 33094210, 2020). "We supposed that the expression of AR increased by short stimulation of androgen in vivo and in vitro; while the expression of AR might be inhibited due to the increased activity of AR in a chronic environment of hyperandrogenism like PCOS." (PMID 32488141, 2020). "Therefore, although chronic DHT exposure from 3 weeks of age increases AR expressing neurons in the brain, the GnRH neuronal network changes and hyperactive LH secretion associated with prenatal androgen excess are not evident." (PMID 35267218, 2022). "Given the variation in the CAG repeat length of the androgen receptor (AR) gene and its inverse effect on the receptor activity, the alleles with short CAG repeat length are expected to result in amplified androgen receptor activity, resulting in a state of hyperandrogenism." (PMID 20865044, 2010). "The role of hyperandrogenism in the ovulation defects observed in PCOS-like mouse models was elegantly demonstrated by comparing global and cell-specific androgen receptor (AR) knockout mouse lines treated with dihydrotestosterone (DHT) or with AMH." (PMID 40252252, 2025). "Using cre-lox transgenics, GABA-specific androgen receptor knockout (GABARKO) mice were generated and exposed to either acute prenatal androgen excess (PNA) or chronic peripubertal androgen excess (PPA)." (PMID 38788194, 2024). "Dyslipidemia in PCOS is related to hyperandrogenism, in which androgens decrease the catabolic clearance of LDL by interacting with the androgen receptor (AR)." (PMID 38276279, 2024). "Components of cow milk, such as casein, whey proteins, hormones, and growth factors, can elevate androgen receptor activity by increasing insulin and IGF-1 levels, leading to hyperandrogenism and potentially exacerbating HS symptoms." (PMID 39768986, 2024). "Epidemiological studies have shown that an increased risk of EC is associated with increased exposure to androgen, including variation in AR genes 30, 31 and PCOS, leading to hyperandrogenism." (PMID 32913460, 2020). "Hyperandrogenism in a large fraction of the PCOS cases suggests involvement of androgens and the AR gene in the etiology of this disorder." (PMID 24116069, 2013). "Cell type–specific AR knockout studies in other PCOS-like models indicate the importance of the largely glutamatergic KNDy neurons (co-expressing kisspeptin, neurokinin B, and dynorphin) in androgen excess–mediated dysfunction." (PMID 38788194, 2024). "PNA treatment of AR knockout (ARKO) mice does not cause hyperandrogenism, disrupted estrous cyclicity, or altered ovarian morphology, suggesting that the PNA-induced, PCOS-like mouse phenotype is dependent upon AR signaling." (PMID 32310267, 2020).
hyperandrogenism (continued). "Pathophysiological functions of genes are primarily responsible for the synthesis of proteins that have role in PCOS before hyperandrogenism including GnRHR, FSHβ, FSHR, LHCGR, CYP19A1, HSD17B, AR and SHBG, and their effects in PCOS of human have been confirmed." (PMID 30944702, 2019). "Vascular reactivity showed similar alterations: in females, testosterone constricted the ACA only after combined VDD and hyperandrogenism, whereas in males VDD resulted in increased testosterone-induced contractions in spite of decreased androgen receptor expression." (PMID 31083690, 2019). "Hyperandrogenism in PCOS, and inverse correlation between androgen receptor (AR) CAG numbers and AR function, led us to hypothesize that CAG length variations may affect PCOS risk." (PMID 24116069, 2013). "In view of strong evidence supporting relation between CAG length and AR activity, it is reasonable to propose that variation in CAG repeat numbers may contribute to hyperandrogenism, and hence to PCOS." (PMID 24116069, 2013). "It suggested that AR-overexpression could block out the effect of MTNR1A, and AR acted as an important downstream factor of MTNR1A in aromatase production, thus playing a vital role in the PCOS-related pathophysiological process of androgen excess." (PMID 36353509, 2022). "Therefore, it is likely that the over-activation of nuclear AR signaling is responsible for some, if not all, of the gravid uterine dysfunction that results in infertility in pregnant rats under conditions of hyperandrogenism and insulin resistance." (PMID 34180022, 2021). "However, prenatal androgen exposure that leads to postpubertal hyperandrogenism does not increase body weight and results in only very mild metabolic disturbances, suggesting that AR signaling is not elevating NPY activity." (PMID 33094210, 2020). "It has been previously documented that AR protein expression is upregulated in the endometrium of PCOS patients, regardless of the presence of hyperandrogenism." (PMID 39080028, 2024). "Androgen excess, a key feature of PCOS, may impede negative feedback, as long-term blockade of the androgen receptor in women with PCOS can restore sensitivity to ovarian steroid hormones." (PMID 33094210, 2020).
Infertility (70 papers, 2011 to 2025). "The AR is an important gene that is deficient or has a loss of function in animals with infertility." (PMID 40075943, 2025). "As the testis is a major regulator of sperm production capacity, it has been presumed that infertility in this hybrid species results from AR deficiency in the testicular cells." (PMID 40075943, 2025). "A comparative analysis of each of the common CAGn alleles in infertile men and controls revealed statistically significant (p < 0.05) differences for three polymorphic variants of the AR gene containing 21, 24 and 25 trinucleotide repeats." (PMID 39596257, 2024). "In our cohort of infertile Russian men, these allelic variants accounted for approximately 29% of all detected AR gene alleles in this group." (PMID 39596257, 2024). "The aim of the study is to evaluate the CAGn polymorphic locus in exon 1 of the AR gene and to determine the frequency of its different allelic variants in a large cohort of infertile Russian men and to compare them with fertile Russian men." (PMID 39596257, 2024). "In both Russian infertile men and fertile individuals (controls), AR gene variants with 20 to 24 CAG repeats were more common, with a frequency of more than 10% each in the studied sample." (PMID 39596257, 2024). "In an earlier review, it was noted that longer AR CAG repeats were associated with infertility and impaired spermatogenesis of different severity." (PMID 36142533, 2022). "Recently, we conducted a study on a group of azoospermic Jordanian infertile males and analyzed them for common mutations in the Y chromosome, in addition to the androgen receptor (AR) gene." (PMID 34190021, 2022). "Two studies demonstrated that hormone therapy improves sperm count in infertile patients with AIS with AR mutations (p.V686A and p.N727K) and helps them become fathers." (PMID 36159980, 2022). "Future research should investigate the residue levels of these newly identified antiandrogenic PFASs in humans and their associated health outcomes related to AR signaling pathway disruption such as infertility, cancer, and reproductive development." (PMID 35093747, 2022). "Since the dysregulation of the AR is associated with infertility, further studies have to confirm if the identified dysregulation is regressive after a declining infection." (PMID 35453608, 2022). "In a mouse model, termed “specificity affecting AR knock-in” (SPARKI) it was found that loss of AR binding to such selective AREs resulted in infertility (in male animals) due to impaired sperm maturation in the epididymis." (PMID 33572755, 2021). "The importance of Sertoli cell-specific AR signalling in germ cell differentiation has been demonstrated in knockout mouse models in which the loss of AR in Sertoli cells resulted in infertility." (PMID 31963729, 2020). "In the present study, we investigated the distribution of the androgen receptor CAG polymorphism in the infertile population from Beheshti infertility center (Kashan, Iran), compared to normal samples from the same area." (PMID 30713477, 2018). "AR-knockout mice are infertile and display abdominally located testes and developmental arrest of spermatocytes, round and elongated spermatids, implicating that AR-deficient Sertoli cells block spermatogenesis by prohibiting Sertoli cell maturation." (PMID 28152522, 2017). "Although several studies have investigated theproposed association between CAG repeat lengthin AR gene and infertility, these reports have yieldedconflicting results." (PMID 26246877, 2015). "Only a single X-linked gene has been shown to definitively contribute to an infertility phenotype, the androgen receptor (AR), leaving huge scope for further experiments on this chromosome." (PMID 24914684, 2014). "A non-linear relationship between infertility and AR CAGn has also been proposed, such that men with longer or shorter AR CAGn than the median (22–23 repeats) are at a 20% increased risk of infertility." (PMID 23467468, 2013).
Infertility (continued). "This suggests that a deficiency in SRD5A2 production in the epididymis may result in hybrid infertility, as it can subsequently cause incomplete AR signal transduction and altered spermatozoa physiology." (PMID 40075943, 2025). "Collectively, our results demonstrate that the miR-29ab1/Zfp36/AR axis in the hypothalamus plays a pivotal role in the regulation of aggression and mating in male mice, providing a potential therapeutic target for treating infertility caused by low libido." (PMID 39684798, 2024). "Overall, the results of the present study suggested that both the indicated ligands (cypermethrin and deltamethrin) have the potential to disrupt the AR signaling function and might subsequently affect the male reproductive functions, causing infertility." (PMID 37187621, 2023). "Therefore, it seems that other observational studies are needed to elucidate novel gene polymorphism of AR and ER-α and their causative role in the risk of infertility among men." (PMID 35958962, 2022). "Table I shows the genotypic frequencies of AR and ER-α variants in the fertile and infertile men." (PMID 35958962, 2022). "A reduced AR level is frequently associated with infertility and testicular cancer development." (PMID 35453608, 2022). "It has been shown that FKBPL is more highly expressed in the testis, acts as an androgen receptor regulator, and may be associated with infertility." (PMID 34212559, 2021). "In addition to this X‐linked neuropathy, the two polymorphic sites of AR gene are intensively studied as risk factors for infertility or cancer." (PMID 32216057, 2020). "Androgen deficiency or loss of functional AR can lead to spermatogenesis and infertility." (PMID 32184896, 2020). "Interestingly, despite the normal appearance of many peripheral androgen target tissues, the AR SUMOylation-deficient male mice were infertile." (PMID 30770815, 2019). "Although the efficiency of haploid sperm generation was relatively low, and other disordered factors or signaling events require modification, our rescue experiments may provide a new lead for the treatment of infertile patients carrying AR mutation." (PMID 26959739, 2016). "In conclusion, the GGN repeat length in AR gene can affect the risk of men infertility." (PMID 26221130, 2015). "BPA serum concentration showed a positive correlation with ERα, ERβ, and AR in both fertile and infertile women, although the strength of this association appeared higher in the infertile group; moreover, in infertile women, BPA showed a specific, positive correlation with AhR and PXR expression." (PMID 23710174, 2013). "Since male and female mice are viable following naturally occurring and engineered loss of function with male mice infertile as anticipated, functional deletion of AR in pigs was hypothesized to provide a genetic containment strategy for males with edited genomes." (PMID 37699945, 2023). "Previous studies indicated that androgen receptor (AR) knockout, whether in Sertoli cells (S-AR−/y) or total AR knockout (T-AR−/y) in mice, induces spermatogenesis arrest at the diplotene premeiotic stage, causing oligospermia and infertility." (PMID 29670053, 2018). "AR-CAG polymorphism could be an effective way of evaluating the risk of infertility." (PMID 26962784, 2016). "But only% of the PAIS cases had an AR gene mutation.PAIS may reveal as apparently normal maleexcept for infertility (infertile male syndrome)or characterized by external ambiguous genitaliawith normal development of epididymis, vas deferensand seminal vesicles (Reifenstein syndrome,5-8)." (PMID 24520507, 2014). "Interestingly, aberrant androgen-AR mediated effects have been linked to infertility." (PMID 23947778, 2013). "This study explores the infertility observed in hybrid male cattle–yaks, focusing on the roles of the androgen receptor (AR) and 5α-reductase isoform 2 (SRD5A2) in the epididymis." (PMID 40075943, 2025).